SKAP1 (src kinase associated phosphoprotein 1)
Description:
Positively regulates T-cell receptor signaling by enhancing the MAP kinase pathway. Required for optimal conjugation between T-cells and antigen-presenting cells by promoting the clustering of integrin ITGAL on the surface of T-cells. May be involved in high affinity immunoglobulin epsilon receptor signaling in mast cells.
Synonyms: SCAP1; SKAP55; HEL-S-81p
Tractability: Antibody: UniProt places it where antibodies can reach, with high confidence; its Gene Ontology location is reachable by antibodies, with high confidence; the Human Protein Atlas places it where antibodies can reach. PROTAC: ubiquitination databases record sites on it; its protein half-life has been measured.
Gene: Protein-coding gene on chromosome 17 (48,133,437 to 48,430,275, reverse strand). Ensembl gene ENSG00000141293.
Subcellular location: Cytoplasm; Nucleus; Cell membrane
Subcellular location (Human Protein Atlas): Nucleoplasm; Plasma membrane; Cytosol
Gene Ontology:
Molecular function: protein binding; protein kinase binding; protein phosphatase binding; SH2 domain binding; SH3 domain binding
Biological process: positive regulation of adaptive immune response; positive regulation of cell-cell adhesion mediated by integrin; positive regulation of cell-matrix adhesion; positive regulation of DNA-templated transcription; positive regulation of heterotypic cell-cell adhesion; positive regulation of integrin activation; positive regulation of leukocyte cell-cell adhesion; positive regulation of transcription by RNA polymerase II; T cell receptor signaling pathway
Cellular component: cytoplasm; immunological synapse; nucleus; plasma membrane; plasma membrane raft; cell-cell junction; cytosol; T cell receptor complex
Genetic constraint (gnomAD): Loss-of-function variants: 18 observed, 23.97 expected, observed/expected ratio (o/e) 0.75, 90% interval 0.52 to 1.11. The upper end of that interval is the gene's LOEUF score, 1.11, which puts it in group 4 of 6, group 1 being the genes least tolerant of losing a copy. Missense variants: 211 observed, 241.62 expected, observed/expected ratio (o/e) 0.87, 90% interval 0.78 to 0.98. Synonymous variants: 82 observed, 87.73 expected, observed/expected ratio (o/e) 0.93, 90% interval 0.78 to 1.12.
Homologues: Orthologues: chimpanzee SKAP1 (99% identical), macaque SKAP1 (97% identical), dog SKAP1 (89% identical), pig SKAP1 (88% identical), rabbit SKAP1 (87% identical), mouse Skap1 (82% identical), rat Skap1 (77% identical), guinea pig SKAP1 (74% identical), zebrafish skap1 (52% identical), tropical clawed frog skap1 (48% identical). Paralogues in human: SKAP2 (42% identical).
Diseases named in the same sentence as SKAP1 in open-access papers:
SKAP1 is named in the same sentence as 27 diseases in open-access papers, as found by Europe PMC text mining. Sharing a sentence is not in itself a finding about the gene and the disease. The quoted sentences say what the papers report.
ovarian carcinoma (7 papers, 2014 to 2023). A malignant neoplasm originating from the surface ovarian epithelium. "The SKAP1 locus has been previously associated with ovarian cancer." (PMID 36929174, 2023). "In addition, a closely situated ovarian cancer risk association around the SKAP1 gene had also been targeted for fine-mapping by the Ovarian Cancer Consortium (OCAC), providing additional SNPs covering this chromosomal region." (PMID 24550738, 2014). "Among genes previously linked to ovarian cancer, tests of LIME1, GPR162, STAB1, and SKAP1 resulted in unadjusted p-values <0.05." (PMID 34449791, 2021). "Among 86 genes linked to ovarian cancer in previous publications, our data contained expression values for 42, and of these, tests of LIME1, GPR162, STAB1, and SKAP1, resulted in unadjusted p<0.05." (PMID 34449791, 2021).
breast carcinoma (5 papers, 2012 to 2025). "Studies have shown that Src kinase-associated phosphoprotein 1 (SKAP1) promotes cell proliferation and invasion and is associated with poor prognosis in colorectal cancer, malignant fibrous histiocytoma, and breast cancer." (PMID 37511629, 2023). "Reduced SKAP1 expression is also associated with worse survival in TCGA bladder and breast cancer, with a similar but insignificant trend in prostate and numerous additional cancers." (PMID 34059701, 2021). "In the prior research, it was found that CCDC25 is a NET-DNA sensor on the surface of breast cancer cells, and that colon cancer cell proliferation can be driven by the interaction between NETs triggered by SKAP1 and CCDC25." (PMID 40148973, 2025). "Several of the genes involved are also in signalling pathways relevant to breast cancer: ERBB2, NRIP1 and BCAS3 are involved in estrogen receptor function and APPBP2 with androgen receptor; while TAOK1 and SKAP1 are involved in MAPK signalling and DEPDC6/DEPTOR regulates mTOR signalling." (PMID 23260012, 2012). "Several of the fused genes are also recurrently broken in a substantial proportion of breast cancers, as judged by copy number steps in array-CGH of 1000 breast tumours: around 10% have breaks in ERBB2, BCAS3 and SKAP1, while COL14A1, TIAM1, USP32, TAOK1 are broken in around 4%." (PMID 23260012, 2012). "It is not clear whether SKAP1 is upregulated by fusion as its expression was very variable among normal and breast cancer cell lines." (PMID 23260012, 2012).
endometrial cancer (5 papers, 2018 to 2024). Primary or metastatic malignant neoplasm involving the endometrium (mucous membrane that lines the endometrial cavity). "In this study we report a risk association between loss-of-function variants involving SKAP1 (OR: 2.4, p = 0.008) and endometrial cancer risk, which is consistent with these findings." (PMID 39495297, 2024). "Our loss of function GWAS recapitulated risk associations identified in endometrial cancer SNP-studies, including variants involving SKAP1." (PMID 39495297, 2024). "According to a transcriptome‐wide association study, low src kinase‐associated phosphoprotein 1 (SKAP1) expression in blood increases endometrial cancer risk." (PMID 39233332, 2024). "Other potential candidates for gene alterations correlated with both endometriosis and endometrial cancer are located nearby the SKAP1 and DUSP6 genes." (PMID 35563789, 2022). "Three of the TWAS candidate susceptibility genes (EIF2AK4, SKAP1, and SNX11) have been recently identified as potential regulatory targets of endometrial cancer GWAS risk variation through enhancer-promoter chromatin looping studies." (PMID 34675350, 2021). "The associations of CYP19A1, SKAP1, HEY2, EEFSEC, and EVI2A were supported by colocalization of eQTL and GWAS signals in at least one of the relevant tissues; thus, these five genes were prioritized as candidate endometrial cancer susceptibility genes." (PMID 34675350, 2021). "However, gene alterations in PTRD as well as in SKAP1 and DUSP6 regions require further experimental studies to validate their actual contribution to the development of endometriosis and endometrial cancer." (PMID 35563789, 2022).
colorectal cancer (4 papers, 2023 to 2026). A primary or metastatic malignant neoplasm that affects the colon or rectum. "SKAP1 promotes cell proliferation and invasion and is associated with poor prognosis in colorectal cancer." (PMID 41516419, 2026).
endometriosis (4 papers, 2018 to 2023). The growth of functional endometrial tissue in anatomic sites outside the uterine body. "Expression of four of the genes (EEFSEC, GDAP1, ADK, and SKAP1) was also significantly associated with endometriosis risk when SMR analyses were conducted using the eQTL and GWAS summary statistics." (PMID 37587191, 2023). "Similarly, SKAP1 and MLLT10, candidate genes for endometriosis, ovarian cancer and asthma, have also been linked to adhesion and immune regulation and hematopoietic differentiation." (PMID 37159502, 2023). "Genes shared between endometriosis, uterine fibroids, ovarian and endometrial cancer, asthma and migraine (CDC42, WNT4, SMAD3, SKAP1) were enriched in cell adhesion pathways." (PMID 37159502, 2023).
colon cancer (3 papers, 2024 to 2025). "In colon cancer, NETs promote src kinase-associated phosphoprotein 1 (SKAP1)-mediated NFATc1/CXCL8 signaling, which dampens NK-mediated tumor killing." (PMID 40442839, 2025). "Herein, Src kinase associated phosphoprotein 1 (SKAP1), an immune cell adaptor, is identified as a novel colon cancer‐related gene." (PMID 39269257, 2024). "Our findings suggest that the SKAP1‐NFATc1‐CXCL8‐NET axis is a novel mechanism underlying colon cancer progression, and that targeting SKAP1 is a potential strategy for colon cancer treatment." (PMID 39269257, 2024). "Using a similar strategy, the present study identified a novel colon cancer‐related gene, Src kinase‐associated phosphoprotein 1 (SKAP1), which was significantly upregulated in colon cancer and closely associated with the prognosis of patients with colon cancer." (PMID 39269257, 2024). "In contrast, the tumor and plasma levels of MPO‐NDA were significantly decreased by SKAP1 knockdown in a mouse model of SW620 colon cancer." (PMID 39269257, 2024). "In contrast, the proportion of neutrophils was markedly decreased by SKAP1 knockdown in SW620 tumors, suggesting that SKAP1 expression in cancer cells promotes neutrophil infiltration into colon tumors." (PMID 39269257, 2024). "In this study, we investigated the role of SKAP1, an immune cell adaptor protein, in colon cancer cells." (PMID 39269257, 2024). "We further investigated the influence of NET inhibition on the therapeutic efficacy of adoptive NK cell treatment in SKAP1‐high colon tumors." (PMID 39269257, 2024). "In colon cancer cells, SKAP1 increased the expression of C‐X‐C motif chemokine ligand 8 (CXCL8) via nuclear factor of activated T cells c1 (NFATc1)." (PMID 39269257, 2024). "This was supported by TIMER algorithm‐based analysis using TCGA database, which showed that colon cancer samples with high SKAP1 expression exhibited significantly higher neutrophil enrichment scores than those with low SKAP1 expression." (PMID 39269257, 2024). "We then investigated which transcription factor cooperates with SKAP1 to enhance CXCL8 expression in colon cancer cells." (PMID 39269257, 2024). "Our findings suggest a complex function of SKAP1 in colon cancer beyond the direct regulation of malignant behavior in cancer cells." (PMID 39269257, 2024). "The CCK‐8 assay showed that SKAP1 overexpression slightly promoted the proliferation of colon cancer cells in vitro." (PMID 39269257, 2024). "Both reparixin and CXCL8‐neutralizing antibodies efficiently inhibited the NET‐enhancing effect of CM from SKAP1‐overexpressing colon cancer cells." (PMID 39269257, 2024). "Future studies are necessary to confirm the SKAP1‐induced interaction between colon cancer cells and neutrophils in human clinical samples." (PMID 39269257, 2024). "Src kinase associated phosphoprotein 1 (SKAP1), an immune cell adaptor, is significantly upregulated in colon cancer cells, leading to increased C‐X‐C motif chemokine ligand 8 expression through a nuclear factor of activated T cells c1‐dependent mechanism." (PMID 39269257, 2024). "Although SKAP1 expression was barely detectable in normal colon epithelial cells, a significant proportion of colon cancer cells showed positive immunostaining for SKAP1." (PMID 39269257, 2024). "Together, these results reveal that SKAP1 expression is substantially increased in colon cancer cells, suggesting a potential oncogenic role of SKAP1 in colon cancer." (PMID 39269257, 2024). "Using CD14 as a marker for PMN‐MDSCs in tumor‐bearing mice, we showed that PMN‐MDSCs also accumulated in SKAP1‐overexpressing colon tumors." (PMID 39269257, 2024). "CXCL8, rather than other neutrophil‐related cytokines, has been identified as the key mediator of SKAP1‐induced interactions between colon cancer cells and neutrophils." (PMID 39269257, 2024).
colon cancer (continued). "Together, these results suggest that increased SKAP1 expression in colon cancer cells promotes NET formation possibly via soluble molecules from cancer cells." (PMID 39269257, 2024). "Similar to our tissue microarray results, SKAP1 expression was significantly higher in three of the four tested human colon cancer cell lines than that in normal colonic epithelial NCM460 cells." (PMID 39269257, 2024). "This recruits neutrophils into the tumor microenvironment and promotes the formation of neutrophil extracellular traps, which potently enhance tumor growth and impair cytotoxic immunity, suggesting SKAP1 as a promising therapeutic target in colon cancer." (PMID 39269257, 2024). "In conclusion, SKAP1 significantly promotes colon cancer growth via the cancer cell/neutrophil NFATc1/CXCL8/NET axis, suggesting that SKAP1 is a potential target for colon cancer therapy." (PMID 39269257, 2024). "The proportion of NET‐forming HL‐60 cells, as determined by flow cytometric analysis of SYTOX green‐positive cells, was also significantly increased by CM from SKAP1‐overexpressing colon cancer cells." (PMID 39269257, 2024). "Similar results were observed in the SW620 colon tumor model where SKAP1 was knocked down instead of DNase I treatment." (PMID 39269257, 2024). "In contrast, SW620 colon tumors with SKAP1 knockdown (SW620‐sgSKAP1) showed slower in vivo growth kinetics and were significantly smaller than control tumors (SW620‐sgControl, P < 0.05)." (PMID 39269257, 2024). "Screening of tumor‐infiltrating immune cells revealed the involvement of neutrophils in SKAP1‐induced colon tumor promotion." (PMID 39269257, 2024). "We overexpressed rather than knocked down SKAP1 in HT‐29 and HCT116 cells because these two colon cancer cell lines expressed relatively low levels of SKAP1." (PMID 39269257, 2024). "Notably, SKAP1 expression in colon cancer cells exerted a significant tumor‐promoting effect in vivo rather than in vitro." (PMID 39269257, 2024). "High SKAP1 levels are independently predictive of poor survival in patients with colon cancer." (PMID 39269257, 2024). "Clinical validation of the SKAP1/NFATc1/CXCL8 axis in colon cancer is also required." (PMID 39269257, 2024). "Moreover, NFATc1 mRNA levels were significantly elevated by SKAP1 overexpression in colon cancer cells." (PMID 39269257, 2024). "Importantly, in mice in which Ly6G+ cells were depleted, the growth‐promoting effect of SKAP1 on colon tumor xenografts was substantially attenuated." (PMID 39269257, 2024). "Furthermore, inhibiting SKAP1‐induced NET significantly enhanced the antitumor efficiency of adoptive natural killer cell therapy in colon tumor models." (PMID 39269257, 2024). "Notably, NET inhibition by SKAP1 downregulation in colon cancer cells markedly enhanced the therapeutic efficacy of adoptive NK cell transfer." (PMID 39269257, 2024). "SKAP1 expression in colon cancer cells significantly promoted neutrophil infiltration and NET formation, which largely contributed to the tumor‐promoting effect of SKAP1, via nuclear factor of activated T cells c1 (NFATc1)‐dependent C‐X‐C motif chemokine ligand 8 (CXCL8) expression." (PMID 39269257, 2024). "Importantly, our experiments further showed that SKAP1 displayed significant pro‐tumor activity in colon cancer and, interestingly, neutrophils were involved in the tumor‐promoting effect of SKAP1." (PMID 39269257, 2024). "SKAP1 expression is significantly increased in colon cancer cells." (PMID 39269257, 2024). "Systemic reparixin treatment largely attenuated the tumor‐promoting effect of SKAP1 and completely abolished SKAP1‐associated infiltration of neutrophils in HCT116 tumors, suggesting that SKAP1 promotes neutrophil infiltration into colon tumors via CXCL8." (PMID 39269257, 2024).
colon cancer (continued). "Given that anti‐CXCL8 and anti‐NET therapies are currently being evaluated in clinical trials for the treatment of solid tumors, our study also proposes SKAP1 as a novel biomarker to identify patients with colon cancer who may benefit from these therapies." (PMID 39269257, 2024). "The current study emphasizes the pro‐tumor role of SKAP1 in colon cancer cells." (PMID 39269257, 2024). "In an in vitro cancer cell/neutrophil co‐culture model, SKAP1‐overexpressing colon cancer cells exhibited a markedly increased proliferative capacity when co‐cultured with neutrophil‐differentiated HL‐60 cells, whereas DNase I treatment largely abolished this SKAP1‐induced proliferation enhancement." (PMID 39269257, 2024). "Furthermore, the inhibition of SKAP1‐induced NETs significantly enhanced the efficacy of adoptive immune cell therapy in colon cancer." (PMID 39269257, 2024). "Notably, SKAP1 regulated the transcriptional expression of NFATc1 in colon cancer cells." (PMID 39269257, 2024). "To determine the functional influence of SKAP1 on colon cancer, we overexpressed SKAP1 in HCT1116 and HT‐29 cells, which presented relatively low SKAP1 expression among the detected colon cancer cells." (PMID 39269257, 2024). "Taken together, these results suggest that CLXCL8 is a key mediator of SKAP1‐induced neutrophil infiltration and NET formation in colon cancer." (PMID 39269257, 2024). "Consistently, treatment with the NFAT inhibitory peptide VIVIT almost completely abolished SKAP1‐induced CXCL8 expression, suggesting that SKAP1 dependents on NFATc1 to increase CXCL8 expression in colon cancer cells." (PMID 39269257, 2024). "NET degradation by DNase I markedly increased the sensitivity of colon cancer cells to NK‐cell cytotoxicity and abolished SKAP1‐induced resistance to NK cell cytotoxicity, indicating an important contribution of NET to SKAP1‐induced immune resistance." (PMID 39269257, 2024). "Soluble molecules may link SKAP1 expression in colon cancer cells and NET formation, therefore, we used a cytokine array to compare the levels of 80 secreted proteins in the CM of SKAP1‐overexpressing and control HCT116 cells." (PMID 39269257, 2024). "The observation that SKAP1 elicits a more powerful tumor‐promoting effect in vivo than in vitro suggests the possible involvement of noncancerous cells in SKAP1‐induced colon tumor promotion." (PMID 39269257, 2024). "NFATc1 knockdown significantly decreased CXCL8 levels in the supernatants of colon cancer cells, whereas SKAP1 overexpression failed to significantly increase CXCL8 levels after NFATc1 knockdown." (PMID 39269257, 2024). "We provide evidence, for the first time, that SKAP1 expression in cancer cells potently promotes the in vivo growth of colon tumors and further revealed that the cancer cell/neutrophil NFATc1/CXCL8/NET axis is the key mechanism contributing to the tumor‐promoting effect of SKAP1." (PMID 39269257, 2024). "Ly6G+ cell depletion significantly inhibited colon tumor growth regardless of whether SKAP1 was overexpressed in cancer cells, underscoring the tumor‐promoting effects of neutrophils in our experiments." (PMID 39269257, 2024). "In addition, increased SKAP1 expression did not change the in vitro migration and invasion abilities of colon cancer cells, suggesting that the direct influence of SKAP1 on colon cancer cells is limited." (PMID 39269257, 2024).
gastric cancer (3 papers, 2023 to 2026). A primary or metastatic malignant neoplasm involving the stomach. "The two loci (DOCK10 and FCN1-FCN2) replicated from CoGaPro1, and the 11 loci replicated from CoGaPro2 (CDK15, CROCC2-SNED1, TLR2-RNF175-SFRP2, WWC2, RELN, ZMYM5-ZMYM2, KLF12, SKAP1, CABLES2, and MIR630) gave further support for these genes being associated with a risk of CRC and gastric cancer." (PMID 41516419, 2026).